BTF3L4 (basic transcription factor 3 like 4)
Synonyms: MGC23908
Tractability: PROTAC: ubiquitination databases record sites on it; its protein half-life has been measured.
Gene: Protein-coding gene on chromosome 1 (52,056,199 to 52,090,716, forward strand). Ensembl gene ENSG00000134717.
Subcellular location (Human Protein Atlas): Cytosol; Nucleoplasm
Gene Ontology:
Molecular function: protein binding
Genetic constraint (gnomAD): Loss-of-function variants: 2 observed, 4.47 expected, observed/expected ratio (o/e) 0.45, 90% interval 0.18 to 1.37. That is too few expected variants to judge how well the gene tolerates losing a copy. Missense variants: 18 observed, 46.23 expected, observed/expected ratio (o/e) 0.39, 90% interval 0.27 to 0.58. Synonymous variants: 9 observed, 16.41 expected, observed/expected ratio (o/e) 0.55, 90% interval 0.33 to 0.96.
Homologues: Orthologues: chimpanzee BTF3L4 (100% identical), guinea pig BTF3L4 (100% identical), macaque BTF3L4 (100% identical), mouse Btf3l4b (100% identical), pig BTF3L4 (100% identical), rabbit BTF3L4 (100% identical), rat Btf3l4 (100% identical), tropical clawed frog btf3l4 (96% identical), zebrafish btf3l4 (96% identical), Drosophila melanogaster bic (64% identical), Drosophila melanogaster uncNacbeta (64% identical). Paralogues in human: BTF3 (83% identical), TAB2 (30% identical), TAB3 (28% identical).
Diseases named in the same sentence as BTF3L4 in open-access papers:
BTF3L4 is named in the same sentence as 9 diseases in open-access papers, as found by Europe PMC text mining. Sharing a sentence is not in itself a finding about the gene and the disease. The quoted sentences say what the papers report.
colorectal cancer (1 paper, 2022). A primary or metastatic malignant neoplasm that affects the colon or rectum. "The results showed that only four genes, including ATP6V1F, PPP1R14B, BTF3L4 and SLC7A5, were oncogenes that are required for cell proliferation of stomach cancer, liver cancer and colorectal cancer." (PMID 36620589, 2022). "The gene expression correlation analysis showed that miR-194 expression showed a negative correlation with the expression of ATP6V1F, PPP1R14B, BTF3L4 and SLC7A5 in gastric cancer, liver cancer and colorectal cancer." (PMID 36620589, 2022).
digestive system cancer (1 paper, 2022). A primary or metastatic malignant neoplasm involving any part of the digestive system. "Our finding highlights that miR-194 exerts a tumor-suppressive role in digestive system cancers by targeting ATP6V1F, PPP1R14B, BTF3L4 and SLC7A5." (PMID 36620589, 2022).
tumor (1 paper, 2022). "Transcriptome sequencing and Genome-wide CRISPR/Cas9 proliferation screening confirmed that miR-194 play tumor suppressive roles in GIC mainly by targeting ATP6V1F, BTF3L4, PPP1R14B and SLC7A5." (PMID 36620589, 2022).
BTF3L4 also shares sentences with these, for which no sentence is quoted: cancer (1 paper); congenital heart defects (1); gastric cancer (1); liver cancer (1); non-small cell lung carcinoma (1); stomach cancer (1).